CD4 (CD4 molecule)
Diseases named in the same sentence as CD4 in open-access papers (continued):
Sharing a sentence is not in itself a finding about the gene and the disease.
melanoma (continued). "Although the number of CD45+ hematopoietic cells was similar in the tumor bed of both tumor subtypes, a significantly higher percentage of CD8+ T cells infiltrated B16 melanoma compared with LLC lung cancer, whereas the percentage of CD4+ T cells remained similar." (PMID 40553564, 2025). "We noted a significant CD8+ T cell–dependent increase of CD4+Foxp3+ Tregs in the tumor bed of LLC- but not B16 melanoma–bearing mice." (PMID 40553564, 2025). "In addition, the melanoma patients with combined anti-PD-1 and anti-CTLA-4 therapies revealed PD-1-expressing CD4+FOXP3- T cells (4PD-1hi), a unique suppressive T cell subset linked to higher tumor burden." (PMID 40857744, 2025). "Furthermore, CD4 T cells can acquire NK cell-activating ligands, such as NKG2DL and NKp46L, from human melanomas, allowing them to activate NK cells in the tumor microenvironment." (PMID 39741180, 2025). "However, there was a significantly higher frequency of cytotoxic T cells (CD8+) and total number of CD4 and CD8 T cells in the Melanoma-Combi-ICI group." (PMID 40313772, 2025). "In particular, functional subtypes within the CD8+PD-1+ T-cell compartment are thought to predict responses to PD-1 blockade in lung cancer, while CD4+ PD-1+ T cells have been reported as non-responders to PD-1 blockade in malignant melanoma." (PMID 41451213, 2025). "Through 64Cu-CD4-Nb1 PET imaging, we could spatially localize CD4+ cells within the TME of both immunologically “cold” B16F10 melanomas and “hot” PyMT breast tumors, discerning minimal variations in CD4+ cell densities in the TME." (PMID 40561008, 2025). "The presence of TILs, particularly CD8+ cytotoxic T cells and certain subsets of CD4+ T helper cells, within the TME is widely recognized as a favorable prognostic marker across multiple solid tumors, including melanoma, non-small cell lung cancer, bladder cancer, breast cancer, and ovarian cancer." (PMID 40475782, 2025). "Patients receiving intratumoral therapy for melanoma had enhanced immune cell infiltration, specifically CD4+ and CD8+ T cells, in the injected lesion and in non-injected lesions." (PMID 40333343, 2025). "Recent studies in melanoma have revealed that neoantigen-specific CD8+ and CD4+ T cells—including cytotoxic and regulatory subsets—can be clonally expanded in response to class I- and class II-restricted neoantigens, contributing to both immune activation and localized immunosuppression." (PMID 40574832, 2025). "In one IHC study, greater infiltrates of CD4+ T cells and the IL-2 receptor (an early activation marker of T cells) were noted in regressing melanoma compared to non-regressing melanoma." (PMID 39825956, 2025). "In melanoma pretreatment tumors, CD4+ T cells from nonresponders had significantly higher activation (for example, TIMD4/TIM3, OX40/EBI3, HLA) and cell cycle cGEP usage (P < 0.05 two-tailed t-test)." (PMID 40903640, 2025). "Additionally, molecular dihydrogen (H2) produced during inulin fermentation can diffuse across the intestinal barrier, contributing to immune regulation by increasing CD4+ and CD8+ T-cell activity and inhibiting melanoma tumor growth." (PMID 41424605, 2025). "Melanoma tissue with higher C2 levels had a significantly higher proportion of M1 macrophages and fewer M2 macrophages, as well as increased levels of CD8+ T cells, activated CD4+ T cells, and plasma cells." (PMID 38473271, 2024). "Moreover, IL-10 and IDO further reduce the activity of NK cells, CD4+, and CD8+ lymphocytes against melanoma." (PMID 39026661, 2024). "As melanoma helper peptides were identified, we developed a vaccine comprising 6 melanoma peptides presented by Class II HLA-DR molecules (6 melanoma helper peptides, 6MHP, NSC#728926), which induced Th1-dominant CD4+ T cell responses in most patients and induced durable clinical activity in some." (PMID 38519525, 2024).
melanoma (continued). "That neither TRBC2, CD4 nor CD8B expression within melanomas was predictive of a response to CPI therapies also supports a bona fide association of response with Vδ1+ cells." (PMID 38172341, 2024). "In addition, the infiltration ratio of CD4+ and CD8+ T cells in the melanoma tissue was also detected by flow cytometry." (PMID 38491004, 2024). "It appears that, in terms of HIV parameters (e.g., viral titer, CD4 + T cell counts), immunotherapy has generally not shown a deleterious impact in melanoma patients." (PMID 39609320, 2024). "Purified siLP-ILCP-derived progeny, purified mature NK cells (from wildtype spleen) or CD4+ T cells (as negative controls also from wildtype spleen) were co-cultured with B16F10 melanoma cells and their killing assessed." (PMID 39242588, 2024). "Furthermore, Flot2–/– mice exhibited an increased frequency of CD4+ and CD8+ tumor-infiltrating lymphocytes (TILs) in the B16F10 melanoma model, specifically including Ki67+ proliferating effector CD4+ and CD8+ cells." (PMID 39499901, 2024). "As expected, NK cells showed cytotoxic activity towards the melanoma cells, whilst the CD4+ T cells did not." (PMID 39242588, 2024). "Upon liver colonization with Wt31 melanoma, the levels of both CD4+ and CD8+ decreased in the liver, but no statistical differences between Stab1 KO and Ctrl were detected." (PMID 38275881, 2024). "Such cytotoxic CD4+ T cells appear to play a key role in limiting tumor progression, particularly those in which tumor antigens are presented by MHCII on cancer cells, among them bladder cancer and melanoma." (PMID 39474427, 2024). "Follow‐up investigations demonstrated that the S. typhimurium‐NY‐ESO‐1 vaccine prompted the development of CD4+ T helper 1 (Th1) cells in melanoma patients without inherent NY‐ESO‐1 immunity." (PMID 39275923, 2024). "Both CD4+ and CD8+ T cells induced Ki67 in a flow cytometric analysis of pre- and post-therapy PBMC samples from 48 MM patients and mouse melanoma models treated with CTLA-4 and PD-1 blockade combinations and monotherapy, with the Ki67+ cells exhibiting a CD45RO+ memory phenotype." (PMID 39273452, 2024). "Nanoscale zinc oxide not only exhibits selectivity against melanoma cells but also induces ICD, which promotes DC maturation, further stimulating the infiltration of CD4+ and CD8+ T cells into the tumor site, thereby preventing tumor growth and distant lung metastasis." (PMID 38998669, 2024). "Remarkably, when an increase in melanoma is detected in specific subgroups of patients, it does not appear to correlate with a decline in CD4 + T cell count at diagnosis or general immune suppression, and SIR does not increase over time after diagnosis." (PMID 39609320, 2024). "Spatial co-localization analysis within the TLS of both melanoma and breast cancer post-treatment biopsies revealed that the closest interactions were observed between CD4+ and CD8+; CD20+ and CD8+ cells, and CD20+ and CD4+ cells." (PMID 38883779, 2024). "Similarly, for three of four melanoma PBMCs, the CD8 subset of cells were generally more oligoclonal (less diverse) compared to CD4 cells." (PMID 38649520, 2024). "Uniform Manifold Approximation and Projection (UMAP) dimensionality-reduced expression profiles revealed clusters containing melanoma, CD8+ or CD4+ T cells, NK cells, monocytes, and small clusters of B cells, endothelial cells, and other minor cell populations." (PMID 39312285, 2024). "In contrast, a decrease in Tn, both in the CD4+ and CD8+ compartments, is observed after ICI treatment, and this could confer a better prognostic in melanoma patients, as it was observed in stage III patients." (PMID 39273452, 2024). "The effectiveness of the model has been proven by the ROC curve, and the miRNAs targeting the screened genes were found out, suggesting that the immune system might impact on the prognosis of melanoma by T cell CD8+, T cell CD4+ memory and NK cells." (PMID 38217549, 2024).
melanoma (continued). "In this regard it should be mentioned that both, the bladder cancer and melanoma study showed elevated expression of SLAMF7 on tumor antigen-specific CD4+ CTL and that targeting SLAMF7 with agonistic antibodies enhanced the cytotoxic activity of CD4+ T cells." (PMID 37965314, 2023). "Subsequent in vivo experiments showed that TRP-1 CD4+ T cells were able to eradicate established MHC-II-deficient, but not TRP-1-deficient HCmel12 melanomas." (PMID 37316667, 2023). "This is further supported by a positive correlation of AICDA gene expression and B cell, plasma cell, CD4+ and CD8 + T cell profiles in melanoma skin tumor metastases, which could also indicate B and T cell crosstalk giving rise to plasma cell differentiation." (PMID 37291228, 2023). "In addition, Ginsenoside Rh2 suppressed melanoma tumor growth and increased the survival in a B16F10 tumor model by enhancing CD4+ and CD8+ T cell infiltration into the tumor tissue." (PMID 36768213, 2023). "Thus, similar to the melanoma mouse model, Ce6-PDT elicits a positive abscopal effect through the inhibition of Treg cells that resulted in the activation of CD4+ and CD8+ T cells." (PMID 36944686, 2023). "Autophagy inhibition, indeed, increases the sensitivity of solid tumors (e.g., melanoma and CRC) to ICIs by enhancing tumor-infiltrating tumor T cells (both CD8+ and CD4+) as well NK cells and other innate immune cells (e.g., DCs, M1 macrophages) in immunocompetent mice." (PMID 38071322, 2023). "Combination of pharmacological inhibition and anti-CTLA-4 antibody led to rejection of established tumors and resistance to secondary challenge in mice after inoculation with melanoma cells, which was mainly achieved through restored CD8+ and CD4+ T cells activity." (PMID 38313431, 2023). "Such future studies should consider investigating additional parameters such as lymphocyte subsets (CD4 T-cells and B-cells) and immunoglobulin G levels, which are more specific to immunosuppression for the purpose of identifying asymptomatic CLL among melanoma patients." (PMID 37946198, 2023). "The VLA-4 positive and LFA-1 negative integrin profile of melanoma cells differs from CD4+ effector T cells, which do express LFA-1 and use the ICAM-1/LFA-1 axis for crawling on the BBB apical face prior to diapedesis." (PMID 37894438, 2023). "Furthermore, expression of LAG-3 on regulatory CD4 T cells identified a more immunosuppressive phenotype, which subsequently hindered CD8 T cell function in Hodgkin’s lymphoma, melanoma and colorectal cancer." (PMID 36445478, 2023). "The number of global CD4+ T cells was similar in human melanoma lesions with or without any regression." (PMID 37526660, 2023). "Here, we report an immunocompetent mCherry reporter mouse model for immune cells that express CD4 either during differentiation or CD4 and/or CD8 in their mature state and perform in vivo imaging of immune and cancer cells within a syngeneic B78 melanoma model." (PMID 37020875, 2023). "Some melanoma patients responding to immunotherapies also have high levels of intratumoral cDC1s and CD8 T-cells, while the other responders have high proportions of cDC2s and CD4 T-cells." (PMID 37190135, 2023). "However, the opposite was observed in another study, which suggested that exosomes released by CD4+ T cells inhibited CD8+ CTL responses and antitumor immunity in melanoma." (PMID 37153615, 2023). "Additionally, it also promotes the infiltration of macrophages, NK cells, CD4+ T cells, and CD8+ T cells, and inhibits the growth of implanted murine melanoma in vivo." (PMID 37740175, 2023). "Also, specificities of analyzed biomarkers in melanoma tumor microenvironment cells were very good for PD-L1 (TILs: 91.67%; M: 96.97%), CD8 (86.67%), CD4 (90.00%, p < 0.001)." (PMID 36836455, 2023).
melanoma (continued). "Although CTLA-4 ICB-mediated depletion of tumour-infiltrating regulatory T cells has not been observed in human cancers such as melanoma, prostate and bladder cancers, an increase in tumour-infiltrating CD4+ and CD8+ cells has been reported." (PMID 35708739, 2023). "Their findings proved that de novo antigens of melanoma mediate immune evasion mainly through HLA-II induction of local negative immune regulatory CD4+Treg cells." (PMID 36646683, 2023). "Consistent with this hypothesis, some tumor cells, including multiple myeloma and some melanoma cell lines, demonstrate intrinsic or IFN-γ-stimulated expression of MHC-II63–65, and the expression of MHC-II in melanoma correlates with CD4+ T-cell infiltration." (PMID 36869048, 2023). "In the present study, we demonstrate that vaccination with ITI-3000 induces potent, antigen-specific CD4 T cell responses and a strong humoral response that were sufficient to delay tumor growth of an orthotopic, syngeneic B16F10 melanoma line expressing LTS220A." (PMID 37711623, 2023). "Combined with re-invigoration of exhausted CD4+ T cells, inhibition of UVR-induced MMP-1 release and suppression of B16F10 melanoma metastases, IK14800 offers an opportunity to gain further insight into mechanisms underlying the development and progression of skin cancers." (PMID 37474630, 2023). "Furthermore, multivariate analysis Cox-proportional hazard regression analyzed the following parameters as the PD-L1, CD4, and CD8 TILs expression patterns to observe their potential prognostic roles in melanoma tumor microenvironment cells." (PMID 36836455, 2023). "In a phase 1 clinical trial, a liposomal RNA vaccine containing four TAA-encoded liposomes for the treatment of patients with unresectable melanoma (NY-ESO-1, MAGE-A3, tyrosinase, and TPTE) induced strong CD4+ and CD8+ T cells immunity and mediated a durable objective response." (PMID 37055849, 2023). "Additionally, studies have reported that TLR7 agonist imiquimod augmented the immunogenicity of peptide vaccine by activating the strong and durable response of CD4+ T cells and CD8+ T cells in melanoma." (PMID 35413927, 2022). "Moreover, significant correlations between high intra-tumoral density of cDC2s, low frequency of Tregs, high CD4+ T cells abundance represent a better outcome of HNCC and melanoma patients." (PMID 36230990, 2022). "It has been reported that CTLA-4 siRNA-loaded nanoparticles could increase the number of CD8+ T cells, decrease the ratio of CD4+ FOXP3+ Tregs and effectively inhibited tumor growth in mice with melanoma." (PMID 34875483, 2022). "In addition, cell counts of CD4+TIM-3+ and CD8+TIM-3+ TIL linearly correlated with tumor cell burden, indicating that progressing B16 melanoma tumors accumulate exhausted TIM-3+ TIL that fail to control tumor growth." (PMID 35193929, 2022). "Previously, it was shown that the use of monoclonal antibodies against Fas did not inhibit the in vitro killing of melanoma cells by CD4 CTLs." (PMID 35572552, 2022). "Furthermore, tumor-specific ICOShi+CD4+IFNγ+ T-cells have been identified as a potential biomarker for anti-CTLA-4 response and prognosis in melanoma and bladder cancer patients." (PMID 35326731, 2022). "Furthermore, in melanoma, sargramostim and ipilimumab combination therapy increased overall survival (OS) and enhanced expression of inducible T-cell co-stimulator (ICOS) on CD4+ and CD8+ T cells over ipilimumab alone." (PMID 36685591, 2022). "We found that the transferred tumor-specific CD4+ T cells efficiently mitigated melanoma lung and liver metastases, independent of CD8+ T, natural killer (NK), and macrophage cells." (PMID 35784297, 2022). "Two recent studies demonstrated that RIG-I activated by short 5′-triphosphate-modified RNA (ppp-RNA) reduced tumor burden in melanoma and acute myeloid leukemia (AML) model, which was dependent on CD4+ T cells, CD8+ T cells and the intact MAVS/IFN signaling in the host." (PMID 35413927, 2022).
melanoma (continued). "In the melanoma samples, ZEB1 level was positively related to CD4+ T cells (R = 0.338, p = 1.20e−13), CD8+ T cells (R = 0.203, p = 1.17e−5), macrophages (R = 0.152, p = 1.12e−03), dendritic cells (R = 0.008, p = 8.67e−1) and neutrophils (R = 0.528, p = 3.15e−34)." (PMID 35232428, 2022). "This indicates that the minimum CAP treatment time (60 s) required to have noticeable effects on the tested melanoma cell lines already would result in the severe cytotoxic and anti-proliferative effects on CD3+, CD4+, and CD8+ T cells grown in a single cell culture." (PMID 35326381, 2022). "Notably, ssGSEA exhibited that activated CD4+ T cells, activated DC and memory B cells were significantly abundant in FGFR Mut melanoma (all P < 0.05)." (PMID 36426352, 2022). "Interestingly, PD-1H was significantly upregulated in both CD4+ and CD8+ T cells in B16-OVA melanoma tumors compared with splenic T cells." (PMID 34905507, 2022). "Furthermore, we observed an elevated infiltration of various immune cells, including DC, M1 macrophages, CD4+ T cells, CD8+ T cells, NK cells, B cells, Th2 cells, and mast cells in our PGS-low score groups among the melanoma cases we analyzed." (PMID 36513682, 2022). "Together, these results show that Activin-A secretion by melanoma cells shifts the composition of tumor immune infiltrates from CTLs and NK cells toward increased non-regulatory CD4 T cells, DCs, and monocytes." (PMID 35580932, 2022). "Recently, dietary fibers were found to influence the human gut microbiota, inducing CD4+ T cell activation and the accumulation of co-stimulator-expressing CD8+ and CD4+ T cells in the tumor of late-stage melanoma patients responsive to anti-PD-1 immunotherapy." (PMID 35684019, 2022). "CD4+ and CD8+ T cells also exhibited various signs of mitochondrial stress following 30 s of CAP treatment, whereas the different melanoma cell lines tested required double (UKRV-Mel-15a) or even quadruple (Ma-Mel-19) the dose of CAP to begin to show signs of mitochondrial stress." (PMID 35326381, 2022). "Increasing trends of IFN-γ production by CD8+ and CD4+ TILs were noticed in scrambled control but not IFNγR1KO melanomas upon anti-CTLA-4." (PMID 36008408, 2022). "Here the authors report CD4-targeted, nanoparticle-based artificial antigen-presenting cells that expand CD4+ T cells capable of lysing tumor cell lysis in vitro, and CD8+ T cells showing antitumor activity in a mouse melanoma model." (PMID 36241639, 2022). "In the example of a melanoma BrM tissue section where tumor parenchyma was surrounded by inflammatory stroma (patient 16), densities of CD3E, CD4, CD8A, and CD8B transcripts were highest in the peritumoral inflammation and in the directly adjacent tumor parenchyma." (PMID 35584630, 2022). "In addition, to verify the relationship between DIRAS2 and immune cells in vivo, we used an IHC assay to detect the positive rate of CD4+ T and CD8+ T cells in the tissues of 20 melanoma patients." (PMID 35651810, 2022). "The percentages of polyfunctional (IFNγ+TNFα+) total MAIT cells and CD4+ MAIT cells were reduced in melanoma patients compared to HD, while no changes in the production of these cytokines by CD8+ or double‐negative (CD4−CD8−, DN) MAIT cells were observed." (PMID 35028137, 2022). "To determine whether CD4+ T cell help led to superior in vivo antitumor efficacy of CD8+ T cell therapies, we used an adoptive transfer model of preestablished murine melanoma." (PMID 36241639, 2022). "Similarly, in human DCs, GFP expression was shown to act as an “adjuvant” to enhance T-cell immunity to the melanoma tumor antigen MART1 and to expand multiple CD4+ and CD8+ T-cell clones." (PMID 35062296, 2022). "The FGFR Mut melanomas exhibited a mild tendency of higher proportion of anti-tumor immune cells, such as CD8+ T cells, activated CD4+ memory T cells, activated DC, activated NK and M1 macrophages, but the difference was not statistically significant (all P > 0.05)." (PMID 36426352, 2022).